ACTA2 (actin alpha 2, smooth muscle)
Diseases named in the same sentence as ACTA2 in open-access papers (continued):
Sharing a sentence is not in itself a finding about the gene and the disease.
vasculopathy (6 papers, 2015 to 2025). "Review of patient’s prior neuroimaging studies demonstrated findings consistent with her history of ACTA2 mutation-related vasculopathy." (PMID 26637293, 2015). "Research onα-SMA and ACTA2 mutations is imperative for understanding the pathogenesisand determining the pertinent management strategies of vasculopathies." (PMID 26934405, 2015). "In order to highlight the potential mechanisms of pertinentvasculopathies and to enhance management strategies, the phenotypes of α-SMAand implications of ACTA2 mutations in vasculopathies are described." (PMID 26934405, 2015). "We report a case of transcatheter arterial embolization for a pseudoaneurysm of a deep femoral artery in a patient with presumptive ACTA2-related vasculopathy." (PMID 34630793, 2021). "This consensus statement focuses on the diagnosis, monitoring and treatment of patient with ACTA2-related vasculopathy including genetic counselling." (PMID 31752940, 2019). "Patients affected by ACTA2-related vasculopathy will usually be diagnosed due to an incidental detection of aortic dilatation, or after an acute dissection." (PMID 31752940, 2019). "Since ACTA2-related vasculopathy is a recently described condition, the phenotypic spectrum and precise risk factors are probably not fully understood." (PMID 31752940, 2019). "The genetic work-up should include review with a clinical geneticist who will assess for traits that can potentially recur in patients with ACTA2-related vasculopathy as well as other, previously unreported traits." (PMID 31752940, 2019). "This consensus statement summarizes our recommendations on diagnosis, monitoring, treatment, pregnancy, genetic counselling and testing in patients with ACTA2-related vasculopathy." (PMID 31752940, 2019).
cardiovascular diseases (5 papers, 2020 to 2022). "The long term implications of making a molecular diagnosis in cases of PBS are significant, as PBS patients harboring a FLNA or ACTA2 mutation may need to adopt surveillance strategies for cardiovascular disease such as moya-moya or TAA." (PMID 32085749, 2020). "In cardiovascular diseases, defects in the function of actin or myosin (ACTA2 or MYH11) result in diminished actin–myosin interactions and lead to diseases." (PMID 34858981, 2021). "In comparison, no mutations in MYH11 and ACTA2 were detected in her father who had no cardiovascular diseases." (PMID 36440024, 2022).
heart disease (4 papers, 2022 to 2024). "To evaluate the development of de novo heart disease after renal injury, we determined expression levels of atrial natriuretic peptide (Anp), brain natriuretic peptide (Bnp), and smooth muscle actin alpha 2 (Acta2), which are sensitive markers of hemodynamic burden and cardiac remodeling." (PMID 39200372, 2024). "The therapeutic candidacy of circRNA ACTA2 was also demonstrated in these mechanistic studies; however, there has not yet been any investigation of circRNA ACTA2 as a biomarker for cardiac fibrosis or heart disease." (PMID 38485860, 2024). "We did not observe specific expression of Acta2 for the ECM-Fib subtype or any other fibroblast subtype in our study even when integrating with data from other murine heart disease models, indicating that in our injury model no classic myofibroblasts developed." (PMID 35641541, 2022).
blood tumors (1 paper, 2025). "ACTA2 serves as a risk factor across all seven types of blood tumors." (PMID 41048997, 2025).
ACTA2 also shares sentences with these, for which no sentence is quoted: thoracic aortic aneurysms and dissections (4 papers); glaucoma (3); Loeys-Dietz syndrome (3); prostate carcinoma (3); type 2 diabetes mellitus (3); aortic valve disease (2); Arthritis (2); atrial fibrillation (2); cardiomyopathies (2); congenital heart disease (2); fatty liver (2); genetic diseases (2); hyperlipidemia (2); hypertrophy (2); Mydriasis (2); pancreatic adenocarcinoma (2); PHACE syndrome (2); seminoma (2); skin cancer (2); Tetralogy of Fallot (2); Vascular Ehlers Danlos syndrome (2); vasculitis (2); acute myocardial infarction (1); adenoma (1); Alzheimer disease (1); ameloblastoma (1); Andersen syndrome (1); anemia (1); Aneurysm - osteoarthritis syndrome (1); aortic insufficiency (1).
A further 90 diseases each share a sentence with ACTA2 in 1 paper.